TSLP (thymic stromal lymphopoietin)
Diseases named in the same sentence as TSLP in open-access papers (continued):
Sharing a sentence is not in itself a finding about the gene and the disease.
atopic dermatitis (continued). "ILCs in the skin are activated by TSLP, IL-33, and IL-25, which are highly expressed in atopic dermatitis." (PMID 32326002, 2020). "This study highlights the critical role of TSLP in T cell migration as well as in the pathogenesis of atopic dermatitis." (PMID 32509598, 2020). "In an intradermal ovalbumin and TSLP model of atopic dermatitis and food sensitization, keratinocyte derived IL-33 was necessary for ovalbumin IgE production." (PMID 33488627, 2020). "TSLP is a cytokine expressed by epithelial cells, including keratinocytes, and plays an important role in allergic inflammation, such as atopic dermatitis (AD)." (PMID 31556482, 2019). "Nociceptors can also sense IL-5 produced during allergic airway inflammation, IL-31 produced during lymphoma-associated itch, thymic stromal lymphopoietin (TSLP) and IL-4 produced during atopic dermatitis, and IL-33 derived from contact with poison ivy." (PMID 30766472, 2019). "In humans, atopic dermatitis is characterized by a high level of TSLP in skin lesions, which is secreted by keratinocytes." (PMID 29670037, 2018). "Reduced inflammation was confirmed histologically and by reduced concentrations of cytokines, which are frequently associated with atopic dermatitis (IL-4, IL-13, TARC) and cytokines for which a major role in the mediation of itch has been described (TSLP)." (PMID 29970189, 2018). "In terms of other tissues composed of stratified squamous epithelium, such as skin, expression of TSLP has been shown to contribute to disease in allergic dermatitis in both human patients and mouse models." (PMID 29259025, 2017). "Keratinocyte-derived TSLP expression is increased in acute and chronic lesions of atopic dermatitis patients." (PMID 29140280, 2017). "In bronchial asthma and atopic dermatitis, TSLP activated myeloid dendritic cells (mDC) and monocytes through its receptor (TSLPR) to abundantly produce Th2-related chemokines including MDC and TARC, resulting in migration of Th2 cells to the lesions." (PMID 28278185, 2017). "Thymic stromal lympopoietin (TSLP) is a cytokine involved in allergic diseases and fibrotic conditions such as asthma, allergic rhinitis, atopic dermatitis, systemic sclerosis and scleroderma." (PMID 29140280, 2017). "Thymic stromal lymphopoietin (TSLP) is known to have an important role in the pathogenesis of atopic dermatitis by mediating an immune response to Th2." (PMID 29140280, 2017). "The expression of thymic stromal lymphopoietin and the activation of signal transducer and activator of transcriptions 3, 5 and 6 were enhanced concomitant with exacerbated allergic dermatitis effects and the activation of NF-kB induced by DINP." (PMID 27863430, 2016). "It was previously shown that level of IL-4 was increased in the serum of allergic rhinitis and allergic children, and TSLP were significantly increased in the serum of atopic dermatitis children." (PMID 27445435, 2016). "TSLP also plays a critical role in a model of atopic dermatitis induced by topical administration of calcipotriol that is independent of T lymphocytes." (PMID 24465642, 2014). "In mice, epidermal overexpression of TSLP results in an atopic dermatitis phenotype characterized by epidermal hyperproliferation, acanthosis, spongiosis, and hyperkeratosis, as well as mast cell infiltration in the dermis." (PMID 24843010, 2014). "The expression of TSLP is increased in keratinocytes of patients with atopic dermatitis and keratinocyte-specific expression of TSLP induces atopic dermatitis-like inflammation in the skin of mice." (PMID 24465642, 2014). "Neutralization of TSLP completely abrogated the atopic dermatitis phenotype in TPA treated EPI−/− mice." (PMID 24843010, 2014). "Keratinocytes too can secrete functional TSLP after stimulation with pro-inflammatory or Th2-driven cytokines, and induces DC activation in human skin lesions of atopic dermatitis." (PMID 24204367, 2013).
atopic dermatitis (continued). "In humans, TSLP expression is elevated in the lesion skin of atopic dermatitis patients and in the lungs of asthmatic patients." (PMID 23437132, 2013). "Similarly, in the meta-analysis of 14 studies assessing TSLP concentration in the blood of patients with atopic dermatitis, the heterogeneity was also high (I2 = 97.46%)." (PMID 41357156, 2025). "In addition, Tezepelumab is a novel bispecific antibody that can target thymic stromal lymphopoietin (TSLP) and IL-33 simultaneously and shows potential in the treatment of severe atopic dermatitis." (PMID 40909165, 2025). "Its integrated actions map directly onto primary dermatological conditions, atopic dermatitis (Th2/TSLP blockade), psoriasis (NF-κB suppression), photoaging and wound repair (Nrf2 activation), fibrosis and barrier loss (PPARγ signaling), and pruritus (opioid/TRP pathways)." (PMID 41304852, 2025). "Resveratrol can decrease the expression of TSLP, which is a marker of atopic dermatitis." (PMID 38666929, 2024). "Natural flavonoid quercetin reduces TSLP levels in an in vitro atopic dermatitis model using human keratinocytes, and dietary fish oil or fermented fish oil (both are rich in long-chain unsaturated fatty acids EPA and DHA) reduces TSLP expression in atopic dermatitis-affected mouse ear tissue." (PMID 38931338, 2024). "Thymic stromal lymphopoietin (TSLP), is a highly expressed cytokine in atopic dermatitis." (PMID 38500882, 2024). "The topical application significantly reduced dermatitis scores, mast cell infiltration, and serum levels of immunoglobulin E (IgE), IFN-γ, interleukin (IL)-4, IL-17, and thymic stromal lymphopoietin (TSLP), demonstrating its effectiveness in treating atopic dermatitis (AD)." (PMID 38790668, 2024). "Whether TSLP activates the eosinophils of patients with atopic dermatitis or allergic patients more than it activates those of healthy individuals has not been fully elucidated." (PMID 39624446, 2024). "Experimental model of food allergy in mice demonstrated that epicutaneous sensitization to OVA or peanut through an atopic dermatitis-like skin led to TSLP-dependent infiltration of basophils to the skin and basophil-derived IL-4 production that induce enhanced Th2 response in the skin." (PMID 36904070, 2023). "For instance, high amounts of thymic stromal lymphopoietin (TSLP) in patients with atopic dermatitis activate T helper (Th) cells to produce Th2 cytokines (e.g., Interleukine (IL)-4, IL-5), which in turn can directly lead keratinocytes to further produce more TSLP." (PMID 37511139, 2023). "Previous studies have shown that TSLP plays an important role in atopic dermatitis." (PMID 37090725, 2023). "For example, the blockade of H4 receptors displayed antipruritic and anti‐inflammatory effects in atopic dermatitis, possibly through the inhibition of both direct sensory nerve stimulation and increased IL‐31 and thymic stromal lymphopoetin (TSLP) production by inflammatory cells." (PMID 36477831, 2023). "FMN was reported to inhibit TSLP levels in keratinocytes and mouse models of atopic dermatitis." (PMID 36673369, 2023). "The roles of IL-4, IL-13, IL-31, and TSLP in the pathogenesis of atopic dermatitis might involve a dysfunctional epidermal barrier and allergen sensitization, which are characterized by intense itching and pruritus." (PMID 37676892, 2023). "In addition to strategies aimed at neutralizing the functions of TSLP in Atopic Dermatitis (AD), recent research has pursued promising new therapeutic avenues, explored in preclinical trials using murine models." (PMID 37515689, 2023). "For example, the inhibition of TSLP, an inhibitory target of atopic dermatitis, was predicted to lead to therapeutic effects in cervical cancer (CC), ovarian cancer (OC), systemic lupus erythematosus (SLE), chronic myeloid leukemia (CML) and congenital muscular dystrophies." (PMID 35758779, 2022).
atopic dermatitis (continued). "In addition, the expression of TSLP in the epidermis has been found to result in a spontaneous disease resembling atopic dermatitis." (PMID 35159975, 2022). "PsV patients could be divided into two clusters; in one of the clusters, Th2-related gene, including TSLP, was inducted significantly higher in lesions of patients than those present in atopic dermatitis." (PMID 36046760, 2022). "In atopic dermatitis lesions, TSLP may contribute to the activation of LCs, which then migrate to the draining lymph nodes and prime allergen-specific Th2 responses." (PMID 35432341, 2022). "Furthermore, TSLP promoter demethylation is detected in skin lesions from patients with atopic dermatitis." (PMID 35432341, 2022). "In particular, TSLP is known to be expressed in keratinocytes from patients with atopic dermatitis." (PMID 35159975, 2022). "Indeed, TSLP is highly expressed by keratinocytes in skin lesions of patients with atopic dermatitis and by airway epithelial cells of individuals with allergic asthma." (PMID 34305908, 2021). "Furthermore, osthole attenuates mouse atopic dermatitis by inhibiting thymic stromal lymphopoietin (TSLP) production in keratinocytes." (PMID 34691215, 2021). "We recently developed a mouse model of atopic dermatitis-like skin inflammation where we could also find TSLP expressed in the skin." (PMID 34833113, 2021). "In addition, obese mice on a high-fat diet show an increase in TSLP production, which is an important driver of atopic dermatitis skin inflammation." (PMID 34069063, 2021). "In contrast, PGE2 also exists at high concentrations in the skin of patients with atopic dermatitis (lesional AD skin: mean 97.2 ng/gm, healthy skin: mean 27.1 ng/gm) and PGE2-EP2 signaling enhances the protective effect against atopic dermatitis by suppressing TSLP production." (PMID 34069063, 2021). "In addition, NFAT is involved in TSLP production in keratinocytes, which leads to psoriasis, eczema, and atopic dermatitis." (PMID 33562140, 2021). "Furthermore, multiple reviews have described the role of TSLP in allergic disorders [atopic dermatitis (AD), airway allergy, and food-hypersensitivity reaction], autoimmune diseases, infections, and cancers." (PMID 34249003, 2021). "In addition, TSLP plays a critical role in the production of IL-4 from Th2 cells in atopic dermatitis through crosstalk between epithelial cells and dermal dendritic cells." (PMID 34946332, 2021). "Experimental overexpression of TSLP in keratinocytes or intradermal injections of this cytokine, by acting on DCs and other mechanisms, result in the development of atopic dermatitis in mice, infiltration of Th2 differentiated CD4+ cells, and systemic Th2 inflammatory responses." (PMID 34571811, 2021). "TSLP/OX40L-induced Th2 responses are critical for the development of atopic dermatitis." (PMID 32326002, 2020). "Whereas the induction of TSLP by IL1β is best established in human and murine keratinocytes in atopic dermatitis, other cell types including immune cells may substantially contribute to TSLP production." (PMID 32285594, 2020). "Furthermore, it was proved that TSLP directly promotes LCs to release Th2 cytokines and attract chemokines in atopic dermatitis." (PMID 33029540, 2020). "More recently, TSLP-neutralizing Ab has been tested in atopic dermatitis patients in a phase II clinical trial and showed promising effects on reducing dermatitis score and itch in combination with topical corticosteroids compared with placebo combined with topical corticosteroids." (PMID 31184997, 2019). "In Th2 hapten TDI-sentitized allergic dermatitis model mice, oral or topical administration of ERα agonist propylpyrazoletriol induced TSLP and IL-33 expression in keratinocytes and promoted scratching behavior; the pruritus might be caused by TSLP and IL-33." (PMID 31547021, 2019).
atopic dermatitis (continued). "Along with TSLP and IL4/IL-13, CXCL10 may cause some of the symptoms of atopic dermatitis, although the role of this cytokine in the disease remains to be fully characterized." (PMID 31782733, 2019). "This suggests that a subset of human patients with atopic dermatitis may be more sensitive to TSLP, and another more sensitive to neutrophils." (PMID 31782733, 2019). "Keratinocytes that lack retinoid X receptors produce TSLP to induce atopic dermatitis." (PMID 29670037, 2018). "In addition, in an atopic dermatitis model mouse, 11 was used as a tool to investigate the expression of thymic stromal lymphopoietin (TSLP), which is triggered in atopic dermatitis and is involved in suppression." (PMID 30103423, 2018). "Cytokines released by keratinocytes in atopic dermatitis, e.g., thymic stromal lymphopoietin (TSLP), alter LC’s ability to induce adaptive immune responses, while “homeostatic” cytokines, such as TGF-β, inhibit LC maturation in situ and are critical for LC retention in the epidermis." (PMID 29238347, 2017). "Genetic variants of TSLP can either induce or protect against the cutaneous inflammation of atopic dermatitis, which may be the result of corresponding increase or decrease in TSLP protein activity." (PMID 29140280, 2017). "TSLP levels have been reported to be increased in the sera of patients with IgAN, women with endometriosis and children with atopic dermatitis, as well as the synovial fluid of patients with rheumatoid arthritis, indicating its role in allergic and non-allergic inflammation." (PMID 29312588, 2017). "However, it is unclear which mechanisms are responsible for translating barrier dysfunction to increased TSLP transcription in human atopic dermatitis." (PMID 28953906, 2017). "For example, in atopic dermatitis (AD), epithelial damage promotes TSLP expression in the skin." (PMID 26992000, 2016). "TSLP expression is sustained as long as barrier defect persists, thus TSLP-mediated activation of dermal innate immune cells and the subsequent local cellular immune response is thought to contribute to the pathogenesis of eczema/atopic dermatitis (AD)." (PMID 26936847, 2016). "High expression of TSLP is found in keratinocytes in allergic dermatitis." (PMID 27863430, 2016). "TSLP was reported to be upregulated in keratinocytes of atopic dermatitis patients." (PMID 24573880, 2014). "Given increased levels of type 2 cytokines, IL-13, IL-4 and IL-5, in acute atopic eczema lesions and enhanced production of epithelial cytokines IL-33, IL-25 and TSLP, it is plausible that group 2 innate lymphoid cells contribute to the pathogenesis of atopic dermatitis." (PMID 25427661, 2014). "In addition, skin and lung over-expression of TSLP induces atopic dermatitis and airway inflammation respectively." (PMID 24204367, 2013). "In this study, only FLG-deficient constructs exhibited higher levels of thymic stromal lymphopoietin (TSLP), which directly stimulated T cell migration and enhanced levels of pro-inflammatory cytokines, thus elucidating new knowledge on the pathogenesis of atopic dermatitis." (PMID 38136325, 2023). "There is the possibility that direct contact of skin with these allergens could trigger signals to initiate a Th2 allergic response and that the epithelial cell-derived cytokines such as TSLP, IL-33, and IL-25 may drive the progression from atopic dermatitis to bronchial asthma." (PMID 33806376, 2021). "However, the therapeutic effect of physcion on atopic dermatitis (AD) through the inhibition of thymic stromal lymphopoietin (TSLP) level remains largely unknown." (PMID 30991764, 2019). "A stronger link of TSLP and disease can be found in patients with atopic dermatitis with an increase of TSLP level and increased frequency of human CD4+Th2 memory cells expressing the prostaglandin D2 receptor (CRTH2), suggesting TSLP may be involved in maintenance of Th2 memory pools." (PMID 23437132, 2013).
atopic dermatitis (continued). "Moreover, another report from the same group showed that S. aureus MVs produced proinflammatory mediators, such as interleukin-6, thymic stromal lymphopoietin, macrophage inflammatory protein-1α, and eotaxin, and induced atopic dermatitis-like skin inflammation." (PMID 22114730, 2011). "In pathological states, these cells display modified gene expression patterns and secrete inflammatory cytokines, such as thymic stromal lymphopoietin (TSLP) and endothelin‐1 (ET‐1), contributing to skin ailments like eczema and atopic dermatitis." (PMID 41388848, 2025). "ADMSC-ApoVs significantly decrease the release of pro-inflammatory cytokines like interferon-γ (IFN-γ), thymic stromal lymphopoietin (TSLP), and IL-4, which are known to be elevated in atopic dermatitis." (PMID 40918108, 2025). "In keratinocytes, BCP specifically counteracts Th2-driven inflammation by suppressing the IL-4/IL-13–MAPK–early growth response 1 (EGR1) axis, which otherwise promotes thymic stromal lymphopoietin (TSLP), a central epithelial alarmin in atopic dermatitis." (PMID 41304852, 2025). "The role of basophils has been investigated in TSLP‐dependent inflammation in mice, using topical vitamin D3 analogue (MC903)‐induced skin inflammation, which is akin to atopic dermatitis in humans." (PMID 39654685, 2024). "Thymic stromal lymphopoietin (TSLP) is an important cytokine produced by epithelial cells and is also found to play a role in atopic dermatitis." (PMID 36613861, 2022). "TSLP-elicited ILC2 promotes allergic inflammation, whereas IL-25 and IL-33 are dispensable for this ILC2 response in an atopic dermatitis-like mouse model." (PMID 35432341, 2022). "TSLP elicits skin basophils, and TSLP-dependent basophil-derived IL-4 promotes ILC2 responses during atopic dermatitis-like inflammation." (PMID 35432341, 2022). "The expression of Th2-inducing cytokines, such as TSLP (thymic stromal lymphopoietin), IL33, and IL25, is increased in atopic dermatitis, and other Th2-mediated disorders." (PMID 34571811, 2021). "Because PAR-2 inactivation directly reduces the expression level of TSLP, PAR-2 has been regarded as a therapeutic target for treating atopic dermatitis." (PMID 34946332, 2021). "The expression of thymic stromal lymphopoietin (TSLP), a cytokine which greatly contributes to the induction of type I allergy, is upregulated in chronic inflammation such as atopic dermatitis and psoriasis." (PMID 31682627, 2019). "High levels of TSLP, but also of IL5 and IL13 have been reported in the skin of atopic dermatitis patients, particularly in those with elevated IgEs." (PMID 27431613, 2016). "Similar to mice injected intradermally with TSLP or genetically engineered to overexpress TSLP in keratinocytes, the increased TSLP expression seen in CCR2−/− mice correlated with development of an atopic dermatitis-like cutaneous inflammation." (PMID 23472158, 2013). "Importantly, in an atopic dermatitis-like cell model induced by TNFα/IFNγ, LF216EV significantly modulated the expression of immune regulatory genes (TSLP, TNFα, IL-6, IL-1β, and MDC), indicating its potential functionality in atopic dermatitis." (PMID 40028723, 2025). "Particularly, given that TSLP is a pivotal upstream cytokine that initiates Th2-driven inflammation and epithelial barrier disruption, PCG is expected to effectively suppress early immunological events in atopic dermatitis." (PMID 41009488, 2025). "Epicutaneous application of house dust mite allergens induces expression of TSLP in nonlesional skin of atopic dermatitis patients." (PMID 39790997, 2024). "While TSLP has been extensively studied as a potential therapeutic target for atopic dermatitis, our model cell line does not express TSLP." (PMID 38181031, 2024). "Another phase 2a study examining treatment of atopic dermatitis with anti-TSLP demonstrated only a trend but no significant improvement for patients." (PMID 33615121, 2021).